CD4 (CD4 molecule)
Diseases named in the same sentence as CD4 in open-access papers (continued):
Sharing a sentence is not in itself a finding about the gene and the disease.
tumor (continued). "The APCs also express class II MHC molecules that present internalized tumor antigens and activate CD4+ helper T-cells as well." (PMID 27019752, 2016). "The failure of immune responses against tumours has been attributed to an active suppression by CD4+FoxP3+CD25+ natural Tregs." (PMID 27341421, 2016). "Tregs were abundant after radiation but more so in Axl Cr#1 compared with the pooled tumours given the increased CD4+ infiltrates." (PMID 28008921, 2016). "In summary, these findings conclusively demonstrate that Id-specific CD4+ T cells induce protective anti-tumor immune responses via indirect recognition of the tumor antigen." (PMID 27626487, 2016). "Compared to that in peripheral blood, the level of IL-10-expressing B cells was further upregulated in resected tumor, while the level of CD4+ cytotoxic T cells was downregulated." (PMID 27136203, 2016). "Since the tumor microenvironment can impair effector T cell function, we also isolated CD4+ T cells from the spleens of mice with actively growing tumor mice to use as responder cells." (PMID 27959896, 2016). "In our study, treatment with B1 AMCE in the tumor-bearing mice group marked an increase of CD4+ and CD8+ T lymphocytes population as well as the NK1.1 level compared to the control untreated group." (PMID 27558166, 2016). "Tumor-infiltrating lymphocytes dissociated from the tumors were stained with anti-CD4, anti-CD8, anti-Foxp3 and anti-IFN-γ antibodies, and then analyzed by flow cytometry." (PMID 27284967, 2016). "We showed that increased pretreatment levels of tumor-infiltrating Tregs and TAMs, and a decreased density of Th2-predominant CD4+ T-cells contribute to poor recurrence-free survival after BCG therapy." (PMID 27221038, 2016). "CD8+ T-cells are responsible for suppressing tumor growth by inducing cytotoxic T-cell killing, whereas CD4+ T-cells are essential to antitumor immune response." (PMID 26727470, 2016). "A logical explanation today is that binding of CD4 by the antibody facilitated tumor antigen processing by DCs and drove antigen‐specific CD8+ T‐cell activation." (PMID 27572622, 2016). "Immunodeficient Rag−/− mice were chosen as tumor hosts because of their capacity to support T cell-dependent tumor clearance after adoptive transfer of naive tumor-specific CD4+ T cells." (PMID 27121060, 2016). "Allogeneic DC-tumor FCs express DC-derived allogeneic HLA class II molecules for direct stimulation of alloreactive CD4+ T cells." (PMID 27240347, 2016). "The percentage of CD4+ TILs expressing PD-1 in tumor tissue was significantly higher than that of CD4+ T cells in AEM." (PMID 27577071, 2016). "Another subtype of CD4+ T-cell that is often present in tumor tissue is regulatory T-cell (Treg) that negatively regulates the immune system." (PMID 27019752, 2016). "These structures are also characterized by an increased CD8+/CD4+ T cell ratio at the tumor periphery and by a co-clustering of T and B cells within these anatomic sites." (PMID 27555845, 2016). "The frequency of OX40-expressing T cells within the conventional CD4 population was also higher in the tumor compared with PBL (P<0.0001)." (PMID 27195113, 2016). "Tumor growth facilitates the induction or recruitment of CD4+ regulatory T cells that secrete IL-10 and TGF-β and suppress effector CD8 T cell responses." (PMID 27075020, 2016). "Mice receiving human PBMCs treated with human sE-selectin showed rapid tumor growth, which coincided with increased intratumoral infiltration of PBMCs, in particular, CD4+ T-lymphocytes." (PMID 27220365, 2016). "A subset of primed MUC1-specific CD4+ T cells induced by DC/MUC1-positive tumor FCs possesses cytotoxicity against MHC class I- and MUC1-positive tumor cells." (PMID 27240347, 2016). "It is critical to stimulate CD4+ helper T cells simultaneously to potentiate the CD8+ T cell-driven anti-tumor response." (PMID 27576783, 2016).
tumor (continued). "Although CTL responses are critical for elimination of tumour cells, role of CD4 T cells and antibodies is also important in modulating anti-tumour immune responses." (PMID 27340370, 2016). "The CTLA4apt-STAT3 siRNA AsiC induced silencing of Stat3 in both CD8+ and CD4+ T cells led to reduced tumor growth in four different murine tumor models and human T cell lymphoma." (PMID 27827876, 2016). "B cells clonotypically diversify the CD4+ T-cell response also to vaccination or tumour challenge, revealing a common effect." (PMID 26728651, 2016). "IFN-γ is produced by CD4+ Th1 T-lymphocytes and plays an important role in immunosurveillance of tumors by activating cytotoxic T-cells that eliminates tumor cells." (PMID 26701207, 2016). "Protection against tumor progression and metastasis is attributed to cellular immunity due to CD4+ nad CD8+ cells." (PMID 27401917, 2016). "Our previous report demonstrates that VA Qu Spez, one of the VA preparations, induces activation of human DCs, and DC-mediated CD4+ T cell proliferation and tumor-specific CD8+ T cell responses as measured by IFN-γ and TNF-α secretion." (PMID 27428940, 2016). "The frequencies of tumor-infiltrating IL-10-expressing B cells and the frequencies of granzyme A and perforin-expressing CD4+ T cells were negatively correlated." (PMID 27136203, 2016). "Flow cytometry analysis revealed lower numbers of CD4+ Th17 cells in the lung tumors from mda-9−/− mice as compared to WT mice only at days 9 and 15 (total accumulation was gradually decreases as tumor progression occurred in both groups)." (PMID 27341128, 2016). "CD4+ T and CD8+ T cells are known to play a central role in regulating antigen-specific immune responses, including those mediated by tumor-associated antigens." (PMID 27821803, 2016). "In consideration of these studies, we believe that certain combinations of human intestinal commensal bacteria can be cultivated to impede tumor growth at local and distant tumor sites by modulating CD4+ T lymphocyte cell activation." (PMID 31456935, 2016). "Increased tumor infiltration by CD4 T cells was observed in both groups treated with MVA-BN-HER2 but was only significant in the combination treatment group." (PMID 26910562, 2016). "In the tumor samples, this was correlated with the number and CD4+/CD8+ ratio of infiltrating T cells and clinical parameters." (PMID 27369431, 2016). "Instead, every tested MUC1 preparation, even non-glycosylated synthetic 9mer peptides, induced interferon gamma-producing CD4+ and CD8+ T-cells that recognized glycosylated variants including tumor-associated MUC1." (PMID 26788922, 2016). "We are also interested in understanding how and what type of host CD4+ T cells are reconstituting in these mice and if they are influencing the generation and memory biology of tumor-specific CD8+ T cells in vivo." (PMID 26885368, 2016). "Our ongoing studies with other tumor models also showed that the same requirement for both CD4 and CD8 T cells for the antitumor effect of DRibble vaccines." (PMID 27874054, 2016). "On the other hand, in the tumor compartment the number ranged from 0 to 21 (median: 1.8, mean: 3.5) for CD4, from 1 to 82 (median: 5.6) for CD8 and from 0 to 15 (median: 1, mean: 1.6) for FOXP3." (PMID 27463005, 2016). "We observed that Tregs from mice with either dormant or actively growing tumor suppressed the proliferation of naïve CD4+ T cells." (PMID 27959896, 2016). "We found that CD4+ T cells in blood, lymph nodes, spleen and the tumors themselves were in equilibrium, and observed a highly significant correlation between the percentages of circulating tumor-specific CD4+ T cells at day 40 and at the time of euthanasia." (PMID 27121060, 2016). "Treatment led to tumor regression and dense immune infiltrate, including many CD4+ and CD8+ cells, in both treated and untreated lesions, some at distant sites which would be consistent with the generation of a tumor specific systemic immune response." (PMID 28191451, 2016).
tumor (continued). "This receptor is expressed on the surface CD4+ effector memory T cells, while their respective ligand, PD-1L, is upregulated on tumor-derived MDSC that induce T cells suppression." (PMID 27294132, 2016). "CD4 T cells themselves have been described as being more efficient at tumor rejection than CD8 T cells." (PMID 27472363, 2016). "Anti-Nrp-1 not only allowed the increased expansion of tumor-derived CD4+CD8a− T cells, but it also activated tumor-derived CD4+ T cells (CD4+CD69+) in IL-10−/− and WT B16/F10 mice." (PMID 27075020, 2016). "Immunofluorescence staining showed that TNFα increased both CD8+ cytotoxic and CD4+ helper T lymphocytes inside the tumor while IFNγ increased CD4+ T cell." (PMID 27342639, 2016). "IL-16 is a pro-inflammatory and pro-angiogenic cytokine which is produced by lymphocytes and some epithelial cells, probably also by tumor cells, and attracts CD4+ cells, especially T-cells." (PMID 27665539, 2016). "Of these immune cells, tumour-infiltrating lymphocytes (TILs) are characterized by an inverted and decreased relationship of CD4+/CD8+ with a reduced capacity to proliferate and an imbalance in the pattern of proinflammatory and regulatory cytokines." (PMID 27293315, 2016). "Among the greatly enriched CD4+ helper T cells in the secondary tumours of mice post PLGA-ICG-R837-based PTT ablation of primary tumours, most of these increased helper T cells were immune-suppressive Tregs." (PMID 27767031, 2016). "Analysis of T cell infiltration showed that FTY720 completely blocked the increase in CD8 and CD4 T cell infiltration at tumor site seen with SCIB1 vaccination." (PMID 27825115, 2016). "The immune cells are originally anti-tumorigenic, presenting tumor antigens and activating CD4+ and CD8+T cells." (PMID 27259252, 2016). "This is an area for further study as the development of the tumour relates closely to the plasma titer value of the virus as well as the degree of immunosuppression as determined by the value of CD4+ T lymphocyte count." (PMID 27034839, 2016). "Immune cells in secondary tumours were collected for further analysis after co-staining with CD4 and Foxp3." (PMID 27767031, 2016). "To identify which T cell populations (CD4 or CD8) were involved in this anti-tumor immunity, we depleted the subpopulations using anti-CD4 and anti-CD8 antibodies prior to tumor inoculation." (PMID 27063435, 2016). "As we all know, Th17 cells are a newly found subset of distinct CD4+ Th effector cells' family named by their signature cytokine IL-17 and are found to play an important role in tumor disease." (PMID 27722177, 2016). "DCs present tumor peptides via and deliver co-stimulatory signals to naïve CD4 and CD8 T cells that mediate tumor-specific cell killing." (PMID 27391442, 2016). "We were able to generate data characterizing both the presence and suppressed status of CD8+ T cells and CD4+ T cells in the tumor microenvironment." (PMID 27539742, 2016). "In this case, Tregs from both BCL1 tumor environments performed similarly in their ability to suppress the proliferation of CD4+ T cells suggesting that the tumor microenvironment also contributes to the functionality of effector T cells." (PMID 27959896, 2016). "In distant tumours, the percentage of infiltrating CD45+ leukocytes and CD4+ T cells with respect to the total number of cells in the tumours were significantly increased in mice treated by PDT of NCP@pyrolipid with anti-PD-L1." (PMID 27530650, 2016). "Although not explicitly evaluated in HNSCC models, OX40 agonism has improved tumor-free survival in a number of solid tumor models through expansion of tumor-specific CD4+ T-cells." (PMID 31093342, 2016). "Initially, we compared the frequency of Tregs, defined as FoxP3+CD25+CD4+ cells, in the blood vs tumor in SCCHN patients." (PMID 27195113, 2016).
tumor (continued). "Central tolerance of CD4+ T-cells is incomplete and peripheral tolerance deepens as the tumor grows and the frequency of regulatory T-cells increases, conceptually reproducing events that govern failure of immune control in patients." (PMID 27471642, 2016). "IL-9 produced by CD4+T cells is responsible for increased survival and function in myeloid DCs, which contribute to anti-tumor immunity." (PMID 27589682, 2016). "Population and function of tumor specific CTL are enhanced by presence of tumor specific CD4+ T cell responses, their lack leads to tumor progression and abrogates the survival of tumor bearing hosts." (PMID 27401917, 2016). "Splenocytes from curcumin-treated tumor bearers had more CD4 and CD8 T cells expressing IFN-γ than did DMSO-treated mice, suggesting a promotion of proinflammatory adaptive responses by curcumin." (PMID 27405665, 2016). "B cells responding to tumor antigen in the presence of CD4+ T cell help proliferated, differentiated into germinal center cells and secreted isotype switched anti-tumor antibodies detectable in the serum." (PMID 27121060, 2016). "Consistently, we confirmed that, as compared to the Tumor group, the samples in Treatment group had greatly higher expression of CD4, CD8 and CD11c, suggesting a strong immune response that induced by the vaccination in the Treatment group." (PMID 27669687, 2016). "A groundbreaking area of immunotherapy has been the identification of antigens expressed by tumor cells and the epitopes thereof that elicit anti-tumor CD4+ and CD8+ responses." (PMID 27071457, 2016). "From the different combinations that were tested we observed that patients with a high FOXP3 stroma/ CD4 tumor expression ratio have reduced PFS (19.4 vs. 37.8 months, p = 0.013) and OS (46.6 vs. 81.2 months, p = 0.012)." (PMID 27463005, 2016). "In order to translate this into a therapeutically useful model, Nishikawa and colleagues activated tumor-specific CD4+ and CD8+ T cells in the presence of GITR signaling, making them become resistant to Treg suppression and able to control tumor growth." (PMID 27242798, 2016). "In this model, the response of naive tumor-specific CD4+ T cells is initiated by tumor-derived antigen presented by host migratory dendritic cells in draining lymph nodes." (PMID 27121060, 2016). "Generally, the CD4/CD8 ratio tends to be lower in tumor patients than in healthy persons, while we observed an increase in the CD4/CD8 ratio in solid tumor patients following decitabine treatment." (PMID 27191266, 2016). "Surprisingly, the Nrp-1-expressing CD4+ T cells obtained from the tumor and TDLN were strongly up-regulated in IL10−/− B16/F10 mice, with the exception of the spleen." (PMID 27075020, 2016). "TIL from digested tumor samples analyzed by flow cytometry displayed relatively high levels of PD-1, as over 30 % of CD4+ TIL (38.2 ± 22.1 %) and 40 % of CD8+ TIL (45.7 ± 26.8 %) were positive for surface PD-1." (PMID 27777771, 2016). "We also analyzed the presence of CD8+ (CD8+CD44hi CD62L−) and CD4+ (CD4+FOXP3−CD44hiCD62L−) effector memory T cells (Tem) in tumors transplanted when the primary anti-tumor responses induced by the vaccination waned." (PMID 27571893, 2016). "The results indicated that in contrast to the mutants, VNP20009 facilitated the migration of CD4+ T cells, macrophages and granulocytes into the tumor." (PMID 27835896, 2016). "The mean number of CD4+ TILs was significantly lower in tumor samples from patients who had died than in tumor samples from surviving patients." (PMID 26927070, 2016). "Immunohistochemically the tumor cells showed an expression of the histiocytic markers (CD4 and CD68) as well as of smooth muscle cell markers SMA and H-Caldesmon." (PMID 28018701, 2016). "In control kidney samples derived from tumor nephrectomies, CD4+RORγt+ cells were detected at low frequencies (<3%)." (PMID 27851911, 2016).
tumor (continued). "TNFR2 expression was also observed for splenic CD4+Foxp3+ Treg cells in naïve and tumor-bearing animals, and human peripheral blood Treg cells, confirming constitutive expression by Treg cells in the periphery of both species." (PMID 27626702, 2016). "Although cytotoxic T cells are the most important mediators of anti-tumor immune responses, induction of CD4 T cells improves clinical outcome, probably by stimulating B cell function." (PMID 27075584, 2016). "T cells (CD8+ cytotoxic cells, CD4+ helper T cells, γδ T cells) and natural killer (NK) cells play vital anti-tumor roles before tumor cells are able to evade immune surveillance." (PMID 27169366, 2016). "In the present study, we report that the presence of the CAR enables recognition and subsequent multifaceted effector functions in both NK and T cells, and also suggests an important antigen-specific role for macrophages and CD4+ T cells in tumor rejection." (PMID 27153556, 2016). "Prior to treatment (day 0), tumors contain a substantial number of CD3+ tumor-associated immune cells (mostly consisting of CD8+ cells, but only few CD4+ cells, and of macrophages (, and unpublished])." (PMID 27579535, 2016). "We show that the TLR2-L SLP conjugates induce significant activation of HPV16-specific CD8+ and CD4+ T cells and robust expression of IFNγ and/or IL-2 by ex vivo stimulated tumor-draining LN-derived T cells of cervical cancer patients." (PMID 27564262, 2016). "The mice were euthanized after 14 days, and DC (CD11c+F4/80-) and CD4+ T cells from the tumor nodules of the lungs were isolated and examined." (PMID 27833081, 2016). "Across a range of human tumors, about 15% of the CD4+ T cell fraction in tumor-infiltrating lymphocytes are RORγ+ cells." (PMID 28123897, 2016). "CTLA-4 expressed by CD4+CD25hiFoxp3+ Treg is thought to contribute to suppression of T effector cells (Teff) and Th, as CTLA-4 deficiency has been shown to decrease both self-tolerance and suppressive function of CD4+CD25+ Treg in tumor immunity." (PMID 27330811, 2016). "In a recent study, TRAIL suppressed hepatocellular tumor growth in mice by inducing specifically tumor-infiltrating CD4+ CD25+ Treg apoptosis, thus, leading to suppression of adverse immune responses." (PMID 26849051, 2016). "Recently, depletion of CD4+ or CD8+ T cells prior to allogeneic tumor inoculation was found to prevent eventual tumor regression in mice, confirming that CD4+ or CD8+ T cells mediate the allogeneic tumor regression at the later stage." (PMID 27448968, 2016). "Both SCIB1 alone (p=0.0086) and addition of PD-1 blockade to SCIB1 (p=0.0321) significantly increased the percentage of CD4 T cells infiltrating the tumor site compared to control." (PMID 27825115, 2016). "Compared with the unconjugated TNFα and IFNγ, the conjugated groups through TCP-1 further increased the infiltration of both CD8+ and CD4+ T cell in the tumor." (PMID 27342639, 2016). "Kranz and colleagues reported that the adoptive transfer of CD4+ T cells expressing affinity-enhanced class I-restricted TCRs inhibited tumor growth." (PMID 27030642, 2016). "Tumor-secreting cytokines are responsible for recruitment of naturally occurring Tregs (nTregs) and the conversion of CD4 Th cells into inducible Tregs (iTregs) at the tumor site." (PMID 27472363, 2016). "The FNA immunophenotyping pipeline we have developed assesses the suppressed status of CD8+ and CD4+ T cells in the tumor microenvironment." (PMID 27539742, 2016). "Elevated percentages of Treg cells are found in the total T cell population isolated from tumor tissue, and these cells can account for 30–50% of CD4+ T cells, depending on the tumor type." (PMID 27999575, 2016). "In contrast, a high ratio of host CD4+ T cells to infused CD8+ T cells was observed in the tumor of mice given LPS prior to the ACT tripartite regimen." (PMID 26885368, 2016).